PDLIM5 (PDZ and LIM domain 5)
Diseases named in the same sentence as PDLIM5 in open-access papers (continued):
Sharing a sentence is not in itself a finding about the gene and the disease.
lung carcinoma (2 papers, 2023). "Mechanistically, they demonstrated that PDLIM5 promotes TGF-β signaling and malignance of lung cancer by specifically interacting with SMAD3 and preventing its degradation." (PMID 36901953, 2023).
mood disorder (2 papers, 2007 to 2013). A cognitive disorder a disturbance in which the person's mood is hypothesized to be the main underlying feature. "In conclusion, our findings support that PDLIM5 is involved in psychiatric disorders, including mood disorders." (PMID 23593136, 2013). "Thus, studies on PDLIM5 expression have shown variable results when using postmortem brains and peripheral leukocytes in patients with mood disorders." (PMID 23593136, 2013). "Thus, the links between PDLIM5 expression and mood disorders, and between PKC and mood disorders, have been reported in humans, while the link between PDLIM5 and PKC has been reported for cell and in-vitro experiments." (PMID 23593136, 2013). "The precise molecular roles of PDLIM5 in mood disorders remain unclear." (PMID 23593136, 2013). "This study aimed to evaluate the effects of decreased PDLIM5 levels on certain behaviors, specifically those related to mood disorders, because significant but not robust evidence for mood disorders in humans has been reported." (PMID 23593136, 2013). "However, the experimental analysis of lowered Pdlim5 expression and the disruption of PKCε translocation on mood disorder in mouse models have not been reported." (PMID 23593136, 2013).
pulmonary hypertension (2 papers, 2020 to 2024). Increased pressure within the pulmonary circulation due to lung or heart disorder. "In pulmonary artery smooth muscle cells (PASMCs), SMC-specific knockout of PDLIM5 enhances hypoxia-mediated vascular remodeling, while overexpression of PDLIM5 inhibits the TGF-β/Smad signal pathway and prevents hypoxia-induced pulmonary hypertension elevation in vivo." (PMID 32848888, 2020).
Stroke (2 papers, 2022 to 2025). Sudden impairment of blood flow to a part of the brain due to occlusion or rupture of an artery to the brain. "Pdlim5 upregulation is a key contributory factor in BBB damage after stroke and knockout Pdlim5 could alleviate this damage." (PMID 40285336, 2025). "In addition, Pdlim5/YAP is shown to be critically involved in BBB damage following stroke." (PMID 40285336, 2025).
autism (1 paper, 2016). Persistent deficits in social interaction and communication and interaction as well as a markedly restricted repertoire of activity and interest as well as repetitive patterns of behavior. "Interestingly, of the autism genes positively correlated with δ-catenin, there is a significant enrichment in genes involved in dendrite morphogenesis, including PDLIM5, SHANK1, CDKL5, and DLG4." (PMID 27822498, 2016).
Cerebral ischemia (1 paper, 2025). Restriction of arterial blood supply to the brain associated with insufficient oxygenation to support the metabolic requirements of the tissue. "YAP mitigates BBB disruption following cerebral ischemia/reperfusion injury and Pdlim5 is known to play a crucial role in BBB damage after acute ischemic stroke." (PMID 40285336, 2025).
COVID-19 (1 paper, 2022). A disease caused by infection with severe acute respiratory syndrome coronavirus 2. "In addition, we deployed validation experiments for local splicing changes of 6 genes (CD74, LRRFIP1, SH3GLB1, MACF1, RPS24 and PDLIM5) between 9 COVID-19 cases and 10 controls by semiquantitative reverse transcription (RT)-PCR." (PMID 35421082, 2022).
mastitis (1 paper, 2024). Inflammation of breast tissue during lactation or postpartum due to an obstructed duct or infection. "Among them, three (ACOT4, PDLIM5, and RAB11FIP5) were also selected as discriminant genes driving the major changes in gene expression profiles of key gene modules related to S. aureus subclinical mastitis in our previous transcriptome analysis." (PMID 38486242, 2024).
memory impairment (1 paper, 2025). "Compared with the young Pdlim5−/− mice, aging did not significantly impair the NOR (p > 0.05) and NLR memory (p > 0.05), indicating that Pdlim5 plays a crucial role in aging‐induced memory impairment in the NOR task." (PMID 40285336, 2025).
mental disorder (1 paper, 2012). A disease that has its basis in the disruption of mental process. "Our results also support previous studies that suggested that the difference in expression level of the PDLIM5 gene in PBLs between patients and control subjects could be used as a potential biological marker for mental disorder." (PMID 23031404, 2012).
non-small cell lung carcinoma (1 paper, 2022). A group of at least three distinct histological types of lung cancer, including non-small cell squamous cell carcinoma, adenocarcinoma, and large cell carcinoma. "In this study, we have prepared nanobubbles loaded PDLIM5 siRNA (PDLIM5siRNA-NBs) to investigate the transfection efficiency and their antagonism in drug resistance in combination with ultrasound irradiation for non-small-cell lung cancer (NSCLC)." (PMID 34964410, 2022).
papillary thyroid carcinoma (1 paper, 2020). "PDZ and LIM domain 5 is additionally up-regulated in papillary thyroid carcinoma (PTC) tissues; elevated PDLIM5 expression promotes the migration, invasion, and proliferation of PTC cells by activating the RAS-ERK pathway." (PMID 32848888, 2020).
tumor (19 papers, 2013 to 2025). "Among them, PDLIM5 is a cytoskeleton-associated protein and has been shown to regulate cell-cell adhesion and tumor progression via binding to a variety of proteins." (PMID 32566649, 2020). "Our findings demonstrate that PDLIM5 knockout significantly diminishes the proliferation and migration capacity of hASCs, consistent with previous studies on the ability of PDLIM5 to suppress metastasis and invasion in tumour cells." (PMID 40457949, 2025). "PDLIM5 (PDZ and LIM domain 5), a cytoskeleton-associated protein, regulates cell migration and tumor progression by binding a variety of proteins through its specific domains." (PMID 41247789, 2025). "Its expression level increases in NSCLC and high PDLIM5 protein expression in tumour tissues is closely related to NSCLC progression and poor prognosis." (PMID 36154921, 2022). "By knocking out a tumor or intracellular PDLIM5, it can inhibit the proliferation of tumor cells, induce cell cycle stagnation, and promote cell apoptosis." (PMID 34964410, 2022). "It is known that PDLIM5 plays an important role in cardiovascular system, nervous system, and tumor system." (PMID 34069539, 2021). "PDLIM5 plays a key role in regulating the proliferation, invasion, and migration of malignant tumor cells by binding to AMPK and regulating its activation and degradation." (PMID 32848888, 2020). "Next, gain- and loss-of-function approaches were employed to elucidate the mechanism of lncRNA AGAP2-AS1/miR-195-5p/PDLIM5 in the processes of cell proliferation, migration and invasion as well as tumor growth." (PMID 33101368, 2020). "First, research on PDLIM5 has mainly focused on its roles in tumor, the nervous system, and the cardiovascular system." (PMID 32848888, 2020). "Meanwhile, silencing PDLIM5 inhibited migration and invasion of tumor cells by reversing the mesenchymal phenotype and a similar result was confirmed in a xenograft nude mouse model." (PMID 29228678, 2017). "The result of qPCR showed that after silencing PDLIM5, the expression of these pro-tumor metastasis factors in PC-3 cells was significantly down-regulated." (PMID 29228678, 2017). "The similar results were also observed in DU145 cells, further confirming that PDLIM5 played a role in promoting tumor metastasis." (PMID 29228678, 2017). "To explore the effect of PDLIM5 on metastasis and invasion of tumor cells, we first designed scratch-wound assays to evaluate the migration and invasion ability by calculating the migration of the two cell lines by the area covered by the migrated cells." (PMID 29228678, 2017). "ONCOMINE microarray data mining showed that PDLIM5 was closely correlated with the prognosis of PCa in terms of Gleason score, tumor metastasis and biochemical recurrence." (PMID 29228678, 2017). "PDLIM5, a scaffold protein, has been reported to be involved in the signalling regulation of membrane-related proteins, cytoskeletal proteins and various signalling molecules along with the progression of various tumours." (PMID 36154921, 2022). "However, we corroborated the tumor-suppressive roles of insertions in Adk and Zbtb20 and in Nipbl, Pdlim5, Ppp1r12a, Tnrc6b, Brd4, Cul3, Ctnna3, Elavl1, Gphn, Nfia, Ptpn12, Taok3, and Rasa1." (PMID 33435458, 2021). "Recent studies have reported that PDLIM5 may be involved in the progression of multiple tumor types, and PDLIM5 may also expand its function by remodeling the cytoskeleton." (PMID 34069539, 2021). "PDLIM5, a cytoskeleton-related protein that tethers protein kinases to the Z-disk in striated muscles, plays a key role in the proliferation and differentiation of the skeletal muscle, nervous, myocardium, and tumor." (PMID 34944246, 2021). "Additionally, lncRNA AGAP2-AS1 inhibition led to an up-regulated expression of miR-195-5p and down-regulated PDLIM5 expression, resulting in delayed tumor growth in vivo." (PMID 33101368, 2020).
tumor (continued). "The results revealed that the tumor volume and weight were considerably elevated in the mice injected with cells stably transfected with pCDNA-PDLIM5 or miR-195-5p inhibitor in the 4th week, which were markedly diminished following PDLIM5 silencing or lncRNA AGAP2-AS1 silencing (p < 0.05)." (PMID 33101368, 2020). "We also used tumor tissues to confirm the effect of PDLIM5 knockdown in vivo by Western bolting." (PMID 29228678, 2017). "PDZ and LIM domain 5 (PDLIM5) is a cytoskeleton-associated protein and has been shown to bind to a variety of proteins through its specific domain, thereby acting to regulate cell migration and tumor progression." (PMID 29228678, 2017). "Second, although the role of PDLIM5 in diseases has been studied, e.g., its expression is up-regulated during tumor development, the specific mechanisms by which it exerts these effects are unknown, and further elucidation of the underlying mechanisms and other functions is warranted." (PMID 32848888, 2020). "According to recent studies, PDLIM5 may be involved in the progression of multiple tumor types." (PMID 32848888, 2020). "The stent protein PDLIM5 (PDZ and LIM structural domain protein 5, ENH) is a novel regulator of SMAD3 stability and critically promotes TGF-β signalling and tumour progression by maintaining SMAD3 stability in NSCLC." (PMID 37685308, 2023). "As a result of PDLIM5 silencing in PC9GR cells, P62 is speculated to be involved in multiple tumour related pathways; however, overall P62 expression was increased in the PC9GR cells." (PMID 36154921, 2022). "Therefore, we hypothesize that PDLIM5 plays an important role in PCa cells because of its interaction with AMPK, which stimulates the proliferation and metastasis of tumor cells by affecting the activation of AMPK." (PMID 29228678, 2017). "Moreover, recent studies have shown that PDLIM5 could participate in cell autophagy by regulating NSCLC drug resistance, helping cells adapt to the stressful environment and promoting cell survival, which leads to tumour drug resistance development." (PMID 36154921, 2022). "Therefore, the specific intervention of PDLIM5 expression may relieve the inhibitory effect of AMPK activation on mTOR under stress state, and then affect cell proliferation, accelerate cell apoptosis, and improve drug sensitivity of tumor cells to EGFR-TKIS." (PMID 34964410, 2022). "Likewise, the absence of PDLIM5 in tumor cells inhibited cell invasion and metastasis." (PMID 29228678, 2017).
cancer (11 papers, 2017 to 2024). A tumor composed of atypical neoplastic, often pleomorphic cells that invade other tissues. "Steroids such as corticosteroid medications play an important role in the development of cancer; it has been reported that 25 single-nucleotide polymorphisms (SNPs) in PDLIM5 interact with steroids, thus affecting the occurrence and development of cancer." (PMID 32848888, 2020). "So we silenced PDLIM5 gene in PC-3 and DU145 cells by using lentivirus expressing short hairpin RNA to observe the phenotype changes of cancer cells and uncover the underlying regulatory mechanism in the tumorigenesis of PCa of PDLIM5." (PMID 29228678, 2017). "Thus, the directional effects of the risk alleles on expression of STK35 or PDLIM5 are consistent with increased cancer risk." (PMID 27704213, 2017). "The PDLIM5 gene has been previously demonstrated to exert an influence on major depressive disorder, schizophrenia, alcohol dependence, bipolar disorder and cancer." (PMID 33101368, 2020). "Dual-luciferase reporter and RNA pull-down/RIP assays were subsequently performed to explore the interactions among lncRNA AGAP2-AS1, miR-195-5p, and PDLIM5, after which their expression was detected in cancer tissues and cells." (PMID 33101368, 2020). "In a study of neurologic tumor, it was found that the transcription factor ID2 binds to the PDLIM5 LIM domains, and, in these cancer cells, high levels of PDLIM5 sequester ID2 in the cytoplasm, preventing neuronal differentiation and promoting cell proliferation." (PMID 32848888, 2020). "GSN, HTRA1, and PDLIM5 were the prognostic genes in the grade 3 carcinoma." (PMID 32640634, 2020). "According to recent studies, PDLIM5 may participate in the progression of many types of cancer including thyroid cancer, lung cancer, breast cancer and gastric cancer." (PMID 29228678, 2017). "Moreover, given the recent discovery that PDLIM5 is an important cancer-related gene, with increased PDLIM5 expression levels in NSCLC associated with poor NSCLC prognosis, siRNA targeting PDLIM5 was chosen to evaluate the siRNA transfection of siRNA-NBs in PC9GR cells." (PMID 36154921, 2022). "PDLIM5 may therefore serve as a therapeutic target in a variety of cancers." (PMID 32848888, 2020). "AMPK signaling exerts regulatory effects on cancer cell adhesion, migration and invasion, which is involved in different mechanisms including disruption of the mTOR, TGF-b, Pdlim5, CXCL12, NF-κB and Akt-MDM2-Foxo3a pathways." (PMID 29245964, 2017). "Finally, we found PDLIM5 plays a crucial role in regulating malignant tumor cell proliferation, invasion and migration by binding to AMPK and affecting its activation and degradation, and may therefore prove to be a potential oncogenic gene in the development and progression of PCa." (PMID 29228678, 2017).
cardiovascular disease (6 papers, 2020 to 2024). "These AMPKs are important and involved in vascular and cardiovascular disease by phosphorylating PDLIM5 in vascular smooth muscle cells to regulate cell migration." (PMID 36620623, 2022). "The expression of PDLIM5 in the ‘cardiovascular disease’ protein category and MYOF in the ‘skeletal and muscular disorders’ protein category were down-regulated in ADSCs cultured in all SFM than in FBS containing media." (PMID 35597800, 2022). "The suppression of PDLIM5 has been found to enhance the nuclear staining of Samd2/3, indicating that PDLIM5 participates in the development of cardiovascular disease by negatively regulating the TGF-β3/Smad2/3 signal pathway." (PMID 32848888, 2020). "Moreover, we also found that Pdlim5 plays an important role in the pathology of some cardiovascular diseases through other post-translational modifications instead of phosphorylation." (PMID 34368251, 2021). "In terms of potential therapeutic strategies for cardiovascular diseases, inhibition of hsa-ABLIM1_0001, hsa-RNF13_0004, and hsa-KIF1B_0001, or overexpression of hsa-MYOM1_0001, hsa-AC096949_0001, and hsa-PDLIM5_0001, may be promising in promoting cardiomyocyte cell cycle and heart regeneration." (PMID 38916964, 2024).
psychiatric disorder (5 papers, 2012 to 2025). A disorder characterized by behavioral and/or psychological abnormalities, often accompanied by physical symptoms. "According to recent studies, PDLIM5 may be involved in tumorigenesis, heart development, and mental illnesses." (PMID 34485842, 2021). "Thus, the study of PDLIM5‐based interaction networks focused on MCHR1‐bearing primary cilia will contribute to improving the understanding of mental illnesses and serve as a basis for developing potential therapies targeting the primary cilia." (PMID 34485842, 2021). "Indeed, it was suggested that alterations to PDLIM5 may contribute to psychiatric disorders." (PMID 38175142, 2024).
myopathy (3 papers, 2018 to 2025). A disease of the muscle in which the muscle fibers do not function properly. "A patient with a benign or minor variation in ZASP may be more susceptible to developing a myopathy if there are other mutations in redundant ALP/Enigma family proteins, such as PDLIM3 or PDLIM5, which are now no longer able to provide the structural integrity of the Z-disc." (PMID 36531944, 2022).
cardiac disease (1 paper, 2018). "We noticed that some of the genes with the largest splicing differences (i.e. the highest splicing index) were pivotal cardiac genes, such as Pln, Pdlim5, and Ttn, that have all been implicated in cardiac disease." (PMID 30076363, 2018).
heart (1 paper, 2022). "MiRNA-27* is therefore a potential novel therapeutic target in chronic heart as its inhibition could result in favorable PDLIM5 upregulation." (PMID 36499336, 2022).
metabolic disorders (1 paper, 2021). "However, the manipulation of Pdlim5 phosphorylation with adenovirus has no significant influence on metabolic disorders in DM mice." (PMID 34368251, 2021).
PDLIM5 also shares sentences with these, for which no sentence is quoted: type 2 diabetes (4 papers); acute myeloid leukemia (1); alcoholism (1); colon cancer (1); colorectal cancer (1); Coronary Heart Disease (1); hepatocellular carcinoma (1); hypertrophic cardiomyopathy (1); immune disease (1); liver cancer (1); melanoma (1); muscular disorders (1); neuroblastoma (1); Obesity (1); ovarian carcinoma (1); pancreatic cancer (1); prostate tumor (1); substance abuse (1).